RELA (RELA proto-oncogene, NF-kB subunit)
Diseases named in the same sentence as RELA in open-access papers (continued):
Sharing a sentence is not in itself a finding about the gene and the disease.
brain ischemia (13 papers, 2012 to 2025). Diminished or absent blood supply to the brain caused by obstruction (thrombosis or embolism) of an artery resulting in neurologic damage. "With the aim of restoring the altered acetylation of RelA and of histones after brain ischemia, we previously studied the combined association of entinostat (MS-275), a specific class I HDAC inhibitor, together with resveratrol, a sirtuin 1 activator." (PMID 29316653, 2018). "RELA, AKT1, JUN, PRKACA, PTGS2, RAF1 and CHUK were identified as four key targets associated with ischemic encephalopathy." (PMID 38285889, 2024). "Of note, we recently showed that VPA and RESV can synergize in promoting neuroprotection in cellular and animal models of brain ischemia by restoring the RelA physiological acetylation state and reverting the histone H3 hypoacetylation." (PMID 35162978, 2022). "We reported that the pathological acetylation profile of RelA and histones in brain ischemia can be corrected by the synergistic combination of low doses of the epigenetic drugs resveratrol and the HDAC inhibitor MS-275 (entinostat)." (PMID 36339574, 2022). "Despite these premises, p50/RelA activation per se appeared to be insufficient to drive pro-apoptotic transcription during brain ischemia." (PMID 32265684, 2020). "During brain ischemia, RelA induced the expression of the 1B isoform of divalent metal transporter-1 (1B/DMT1), the membrane carrier responsible for iron accumulation and brain damage after injury." (PMID 32265684, 2020). "By combining these with previous findings, we can conclude that the aberrant acetylation of RelA, responsible for the pro-apoptotic transcription following noxious brain ischemia, is reverted by a single post-insult administration of MS-275 and resveratrol." (PMID 33246465, 2020). "Activation of NF-kappaB RelA deacetylated at the lysine residues, except the lysine 310, drives pro-apoptotic transcription in noxious brain ischemia." (PMID 33246465, 2020). "The protection was associated with the deacetylation of the lysin 310 (K310) on NF-κB/RelA as well as the deacetylation of H3 histones at the promoter of Bim, a pro-apoptotic target of ac-RelA(K310) in brain ischemia." (PMID 30736313, 2019). "We previously demonstrated that mechanisms affecting the acetylation state of the NF-κB/RelA subunit in brain ischemia can discriminate between protective and neurotoxic activation of the transcriptional factor." (PMID 30736313, 2019). "In previous studies we showed that the acetylation state of NF-κB/RelA (RelA) and histones can discriminate protective and neurotoxic effects elicited by NF-κB in brain ischemia." (PMID 29316653, 2018). "Histone deacetylation, together with altered acetylation of NF-κB/RelA, encompassing the K310 residue acetylation, occur during brain ischemia." (PMID 29316653, 2018). "Chromatin immunoprecipitation (ChIP) assays in cellular or animal models of brain ischemia also established that activated RelA binds the endogenous Bim promoter." (PMID 29316653, 2018). "Induction of anoxia both in vitro (via oxygen glucose deprivation of cortical neurons) and in vivo (using a model of cerebral ischemia) results in a reduction of nuclear RelA/c-REL and RelA/p50 dimers, whereas levels of p50/c-REL dimers remain unchanged." (PMID 28615451, 2017). "In spite of these premises, p50/RelA activation per se appeared to be insufficient to drive pro-apoptotic transcription during brain ischemia." (PMID 26042083, 2015). "During brain ischemia, RelA induced the expression of the 1B isoform of the divalent metal transporter-1 (1B/DMT1), the membrane carrier responsible for iron accumulation and brain damage after injury." (PMID 26042083, 2015). "Activation of RelA subunit displaying reduced grade of general acetylation, but site-specific acetylation of K310, triggers apoptotic gene expression in brain ischemia." (PMID 26042083, 2015).
brain ischemia (continued). "In conclusion, this study shows that site-specific acetylation of RelA at Lys310 switches on the NF-κB-mediated transcription of 1B/(−)IRE DMT1 during the early phase of brain ischemia." (PMID 22666436, 2012). "Previous evidence has shown that activation of nuclear factor kappa B (NF-κB) through RelA acetylation on Lys310 is the prerequisite for p50/RelA-mediated apoptosis in cellular and animal models of brain ischemia." (PMID 22666436, 2012). "Our main finding was that 1B/(−)IRE DMT1 is a target gene for the Lys310-acetylated form of RelA during brain ischemia." (PMID 22666436, 2012). "Our data showed that 1B/(−)IRE DMT1 expression and intracellular iron influx are early downstream responses to NF-κB/RelA activation and acetylation during brain ischemia and contribute to the pathogenesis of stroke-induced neuronal damage." (PMID 22666436, 2012). "The neuronal cell death induced by acetylation of RelA in brain ischemia was prevented by DMT1 silencing and iron chelation." (PMID 22666436, 2012). "We previously reported that the combined administration of low doses of the class-I HDAC inhibitor entinostat (MS-275) and RESV promote the normalization of the RelA acetylation state and revert the pathological histone H3 deacetylation in brain ischemia as well as ALS animal models." (PMID 35162978, 2022). "While the data presented here identified both YY1 and RelA as repressors of the Bim gene, role of RelA as a Bim repressor came in as a surprise because a previous report on RelA in cerebral ischemia model suggested that RelA is a transcriptional activator of the Bim gene." (PMID 23874387, 2013). "A recent study has demonstrated that during brain ischemia, the aberrant activation of NF-κB p50/RelA driving the pro-apoptotic transcription of the Bim gene, relies on both p50/RelA nuclear translocation and RelA site-specific acetylation on Lys310 residue." (PMID 22666436, 2012). "In particular, we previously showed that a specific aberrant acetylation pattern of RelA, characterized by a reduced level of total acetylation, but site-specific acetylation at the lysine 310, RelA Ac(K310), triggers the expression of pro-apoptotic genes in brain ischemia." (PMID 35162978, 2022). "Site-specific acetylation of RelA at the Lys 310 residue was necessary to switch anti-apoptotic p50/RelA, activated after a brief preconditioning ischemia and leading to brain tolerance toward the pro-apoptotic p50/RelA activated after a prolonged harmful brain ischemia." (PMID 32265684, 2020). "Following the evidence that RelA and c-Rel play opposing effects on neuron survival, and prevalence of p50/RelA activation versus p50/c-Rel triggers apoptotic cell death in brain ischemia, we tested whether a constitutive defect in c-Rel protein might affect the brain aging." (PMID 26042083, 2015). "When RelA expression was inhibited using conditional RelA mutants, there was a reduction in infarct volume following cerebral ischemia similar to that seen in mice lacking p50 suggesting that the p50/RelA heterodimers or RelA/RelA homodimers promote ischemic brain damage." (PMID 24265774, 2013). "In particular, a specific pro-apoptotic acetylation profile of nuclear RelA, involving the general deacetylation of lysines but a site-specific acetylation at the lysine 310 [acRelA(K310)], occurs in lethal ischemia but not in protective preconditioning brain ischemia." (PMID 36339574, 2022).
colitis (13 papers, 2016 to 2025). Inflammation of the colon. "Instead, the severe colitis was rather due to the fact that most RelA-deficient Tregs lost Foxp3 expression in the colon and mLN, potentially differentiating in pathogenic effector T cells." (PMID 31749798, 2019). "Our RNAseq data indicate an identity defect of RelA-deficient Tregs, which was first suggested in the colitis model." (PMID 31749798, 2019). "Surprisingly, not only RelA-deficient Tregs were unable to control colitis but the disease was even more severe compared to mice transferred with effector T cells alone." (PMID 31749798, 2019). "This was first suggested in the colitis model, but more direct evidence came from studies where we compared RelA-sufficient and -deficient Tregs in the same environment after cell co-transfer in lymphopenic mice." (PMID 31749798, 2019). "RELA of NF-κB-driven cytokine by myeloid cells is required for colitis-associated cancer growth." (PMID 35517862, 2022). "Then, inflammatory factors may alter drastically stability of RelA-deficient Tregs most of them becoming pathogenic ex-Tregs, as we observed in the colitis model and cell co-transfer in lymphopenic mice experiments, precipitating local inflammation." (PMID 31749798, 2019). "However, one cannot conclude from this latter experiment that RelA plays an intrinsic role in Treg stability, owing to the very severe colitis developed by the mice injected with RelA-deficient Tregs." (PMID 31749798, 2019). "Similarly, mice with IEC-specific deletion of the NF-κB component RELA exhibit increased susceptibility to chemically induced colitis." (PMID 27280399, 2016). "Collectively, these findings indicate that STING, TBK1, and RELA are critical components of IL-10 activation by LGG in the context of colitis." (PMID 39895628, 2025). "We demonstrate that the STING/RELA axis is required for IL-10 production in monocytes with LGG treatment in colitis." (PMID 39895628, 2025). "Non-canonical NF-κB signaling is reported to enhance canonical RelA mediated inflammatory responses in IECs and exacerbated colitis via crosstalk mechanisms." (PMID 35833111, 2022). "In TAMs, canonical NF-κB (RelA/p50) promotes proinflammatory cytokine production (e.g., TNF-α, IL-6) in inflammation-driven cancers (e.g., colitis-associated colon cancer) or immunosuppressive IL-10 secretion in breast and ovarian cancers, fostering tumor growth and immune escape." (PMID 40562870, 2025). "The hepatic RelA/STAT3-CYP enzyme pathway increased primary BAs and exacerbated DSS-induced colitis." (PMID 39767816, 2024). "Rigosertib, an inhibitor of NF‐kB (p65/RelA), was found to ameliorate intestinal fibrosis in DSS‐induced colitis mice." (PMID 37655052, 2023). "Sulfasalazine ameliorates acute colitis in a mouse model induced by trinitrobenzene sulfonic acid, which involves the inhibition of NF-κB activation as well as the downregulation of NF-κB signaling components, such as TLR4, MyD88, and NF-κB RelA." (PMID 40562870, 2025). "Thus, we conclude that RelA and Stat3-driven accumulation of CDCA aggravates intestinal inflammation-induced damage during experimental colitis." (PMID 39137024, 2024). "In agreement with previous findings, a recent publication reported that non-canonical NF-κB signaling enhanced canonical RelA mediated inflammatory responses in IECs and exacerbated colitis." (PMID 35833111, 2022). "In the colitis model, inhibition of STAT3 and RelA expression could ameliorate colonic inflammatory damage by down‐regulating pro‐inflammatory cytokines." (PMID 32815642, 2020).
ovarian carcinoma (13 papers, 2010 to 2025). A malignant neoplasm originating from the surface ovarian epithelium. "Notably, in RELA-knockdown cells, adding a miR-452-5 inhibitor caused significant decreases in ovarian cancer cell viability, sphere formation, and percentage of ALDH+ cells." (PMID 37175530, 2023). "The function of RelA in ovarian cancer is generally considered to be pro-tumor through its role in anti-apoptotic gene activation, promotion of cancer cell stemness, and enhancing migration and invasion." (PMID 40982347, 2025). "We observed similar tumor suppressive characteristics of miR-335-5p across several ovarian cancer cell lines silenced for RELA/RELB." (PMID 37175530, 2023). "We report that hTREX84 is aberrantly expressed in both breast and ovarian cancer and its expression is regulated in part by RelA/p65." (PMID 22952718, 2012). "In this study, we further demonstrated that, as compared to naïve cells, chemoresistant ovarian cancer cells showed increased levels of RELA and STAT5 binding to the Bcl-X promoter." (PMID 20585448, 2010). "Based on our current understanding of RELA/RELB signaling in promoting ovarian cancer proliferation and stem-cell phenotypes, the decreased expression of has-miR-452-5p when RELA or RELB are silenced across OV90, OVCAR8, and ACI23 cells suggests an oncogenic function." (PMID 37175530, 2023). "Similarly, herein, a BCL2A1 promoter-luciferase assay, overexpression, depletion of RELA by RNAi, or inhibition by pharmaceutical approaches in ovarian cancer cells suggest that NF-ĸB signaling is the upstream regulator of BCL2A1 transcriptional activity." (PMID 34572804, 2021). "Both RelA and RelB support ovarian cancer growth in a mouse model." (PMID 31083587, 2019). "In previous works, we have delineated the roles of RELA and RELB in sustaining the ovarian cancer TIC stem-cell like population while showing that enhanced ALDH activity is a marker for TICs." (PMID 37175530, 2023). "In ovarian cancer, CD44+ CSCs enhance self‐renewal and metastasis by upregulating the expression of RelA, RelB, and IKKα and enhancing the activation of p50/RelA dimer." (PMID 34977871, 2021). "It was shown, using CSC from ovarian cancers by magnetic sorting (anti CD133), that NF-κB-mediated migration is activated by an autocrinous loop of CCL5 to RelA." (PMID 31083587, 2019). "Inhibition of either expression or activity of RELA and STAT5B decreased Bcl-xL expression levels and increased carboplatin sensitivity in carboplatin-resistant ovarian cancer cells." (PMID 20585448, 2010). "In this study, we used proteomic analysis and functional screening to identify RELA and STAT5B as the two major proteins involved in carboplatin resistance in ovarian cancer." (PMID 20585448, 2010). "Taken together, these results strongly suggest that RELA and STAT5 co-regulated Bcl-X promoter in response to carboplatin, and conferred chemoresistance in ovarian cancer, in part, through the transcriptional activation of Bcl-xL." (PMID 20585448, 2010). "Similarly, one of the major findings in our study was the upregulation of RELA and STAT5B in recurrent post-chemotherapy ovarian cancer cells." (PMID 20585448, 2010). "Thus, it is likely that RELA and STAT5 proteins cooperate in inducing Bcl-X promoter activity and synergistically enhance Bcl-xL expression in chemoresistant ovarian cancer cells." (PMID 20585448, 2010). "Our findings showed that NF-ĸB p65 (RELA) but not HIF-1α had four putative binding sites on the promoter of BCL2A1, indicating that NF-κB signaling was the upstream inducer of BCL2A1 in ovarian cancer cells." (PMID 34572804, 2021).
supratentorial ependymoma (13 papers, 2018 to 2025). A high grade ependymoma that is located within the supratentorial brain. "Although monozygosity of 22q has been reported in ~ 40% of RELA-fusion positive supratentorial ependymoma (ST-EPN-RELA), the rarity of pathogenic somatic NF2 variants in the majority of intracranial ependymoma suggests a different tumor suppressor gene to be located on chromosome 22." (PMID 36008825, 2022). "ZFTA-RELA (formerly known as c11orf-RELA) fused supratentorial ependymoma (ZFTAfus ST-EPN) has been recognized as a novel entity in the 2016 WHO classification of CNS tumors and further defined in the recent 2021 edition." (PMID 37287693, 2023). "A role for NF-κB RELA in pediatric neuro-oncology is manifested by the RELA fusions in 70% of supratentorial ependymoma." (PMID 31083587, 2019). "Therefore, the biological significance of the RELA fusion gene as a prognostic factor remains ambiguous in supratentorial ependymoma." (PMID 35986385, 2022). "In more than two-thirds of supratentorial ependymoma, which is classified as ST-EPN-RELA, several forms of fusion proteins of ZFTA and RELA, an effector transcription factor of the inflammatory NF-κB pathway, have been identified." (PMID 35087169, 2022). "Also, typical molecular abnormalities of some entities are not covered by our panel (e.g., fusion genes like RELA fusion genes, relevant for supratentorial ependymoma, BRAF-KIAA fusion gene relevant for pilocytic astrocytoma, FGFR fusion genes, potentially targetable)." (PMID 30470264, 2018).